RECQL5 (RecQ like helicase 5)
Diseases named in the same sentence as RECQL5 in open-access papers (continued):
Sharing a sentence is not in itself a finding about the gene and the disease.
cancer (31 papers, 2010 to 2025). A tumor composed of atypical neoplastic, often pleomorphic cells that invade other tissues. "Researchers have created animal models to study complex chromosomal rearrangements linked to cancer and congenital diseases by altering the Recql5 gene in mice." (PMID 38577877, 2024). "Several studies have also indicated that RECQL5 was involved in multiple hereditary cancer susceptibility." (PMID 37180972, 2023). "Of the five different proteins in humans, RECQL1, BLM, WRN, RECL4, and RECQL5, three are associated with germline alterations associated with an increased risk of cancer." (PMID 35782872, 2022). "RECQL5 was a frequently recurrent gene and variant (p.R441Q) compared to East Asian sporadic cancer population (TCGA)." (PMID 34285288, 2021). "In a group of 50 mice deficient in the murine homolog of RECQL5, Recql5, nearly 50% developed cancer within 22 months compared to 6% in wildtype mice." (PMID 32523948, 2020). "The loss of RECQL5 leads to hyper-recombination, which correlates with genomic instability and cancer susceptibility in Recql5–/– mice." (PMID 32369918, 2020). "Mice deficient in Recql5 are more likely to develop cancer, and human cells deficient in RECQL5 display chromosomal instability and elevated sister chromatid exchange events, similar to cells deficient in any of the other RecQ helicases." (PMID 32523948, 2020). "RECQL5 preserves genome stability during transcription elongation, and deletion of RECQL5 increases cancer susceptibility." (PMID 31575041, 2019). "With deletion of the gene in mice also shown to increase cancer susceptibility, it is clear that RECQL5 is an important tumor suppressor." (PMID 29348827, 2017). "This is slightly unexpected given that RECQL5 deficient mice are cancer-prone and suggests that, like several other members of the RECQ helicase family, increased expression of RECQL5 can also be associated with cancer." (PMID 27764811, 2016). "Furthermore, by prioritizing variants with pathogenic potential in genes involved in cancer-associated pathways, we identified RECQL5 as a candidate gene for further follow-up." (PMID 39979679, 2025). "Furthermore, by analyzing variants that occur in genes in cancer-associated pathways, we identified a candidate gene (RECQL5) for further follow-up." (PMID 39979679, 2025). "In addition, beyond findings in the known cancer-predisposition genes, we identified a homozygous RECQL5 variant." (PMID 39979679, 2025). "Additionally, studies on Recql5-deficient mice have demonstrated increased levels of sister chromatid exchange and a heightened susceptibility to various cancers, underscoring the critical role of RECQL5 in genome stability maintenance." (PMID 38577877, 2024). "RECQL5 deficiency is associated with genomic instability and thought to lead to cancer." (PMID 35782872, 2022). "The finding of significant cancer predisposition in mice models deficient in RECQL5 supports the hypothesis that perturbation of RECQL5 levels in either direction can contribute to oncogenesis." (PMID 32523948, 2020). "The present study also demonstrated that RECQL5 expression was high in normal gastric tissues, which may indicate that RECQL5 plays a role in maintaining genome stability and reducing cancer risk in the stomach." (PMID 31897211, 2020). "RECQL5 is essential for maintaining genome stability and reducing cancer risk." (PMID 31897211, 2020). "Moreover, Recql5 knockout mice exhibit elevated levels of sister chromatid exchange and are predisposed to various types of cancer, suggesting that RECQL5 is important for maintaining genome stability as well." (PMID 24836610, 2014). "Therefore, RECQL5 variants are considered candidate genes for human cancers." (PMID 35860595, 2022). "Conversely, BLM, RECQL4, and RECQL5 displayed diverse correlations with stem cell scores across different types of cancers." (PMID 37626815, 2023).
cancer (continued). "BLM, WRN, RECQL4, and RECQL5 were repressed by stromal and/or immune elements in most types of cancer, while RECQL exhibited reverse patterns." (PMID 37626815, 2023). "In contrast no change in growth was seen when wildtype The The potential of RECQL5 as a therapeutic target has been discussed previously in other cancers." (PMID 27764811, 2016). "This evidence along with the fact that mouse Recql5 and human RECQL5 are highly conserved, suggests human RECQL5 may also have an important tumor suppressing function and therefore certain genetic variants that affect the function of this RECQL5 may then alter the risk of cancer in humans." (PMID 27942286, 2010). "Although RECQL5 has not been conclusively linked to human diseases, loss of RECQL5 is known to promote cancer in mice, likely as a result of increased genome instability." (PMID 40624164, 2025). "Increased levels of RECQL5, which is thought to cause HRD, was significantly associated with high HRD score in thoracic malignancies in our cohort, and has been described in several cancers including bladder and breast cancers." (PMID 36964191, 2023). "This process led to preferential killing of RECQL5-expressing cancer cells." (PMID 35782872, 2022). "Previous studies have shown that RECQL5 is an essential factor for maintenance of genomic stability, and that RECQL5 may act as an oncogene in various types of cancer." (PMID 31897211, 2020). "Of the five RecQ helicases, BLM, WRN, and RECQL4 are associated with specific diseases of marked premature aging and cancer predisposition such as Bloom Syndrome, Werner Syndrome, and Rothmund-Thompson Syndrome, respectively, whereas RECQL1 and RECQL5 remain to be associated with specific disorders." (PMID 32523948, 2020). "Small molecules that inhibit RECQL5 might improve the effectiveness of replication fork blockers to treat FA-defective cancers." (PMID 25520194, 2015). "Few reports exist of RTS and RECQL5 helicases as possible cancer targets." (PMID 25620975, 2014). "Although there are no known syndromes associated with germline variants in RECQL5, there are a few studies that suggest that RECQL5 could be a cancer susceptibility gene." (PMID 35782872, 2022). "Functional autosomal recessive loss of three members of the family BLM, WRN and RECQL4, results in hereditary human syndromes characterized by cancer predisposition and premature aging, but despite the finding that RECQL5 deficient mice are cancer prone, no such link has been made to human RECQL5." (PMID 27764811, 2016). "Thus, the level of RECQL5 and BLM could be important when designing a therapeutic regime for FA-defective cancers." (PMID 25520194, 2015). "Because RECQL5- depleted cells show slow proliferation, G2 and M cell cycle arrests and late S-phase cycling defects, resulting in entangled abnormal chromosomes at the M phase, possibly RECQL5 could be challenged, like RECQL1, as a new cancer therapeutic target." (PMID 25620975, 2014).
tumor (16 papers, 2010 to 2025). "Low expression of RECQL5 was significantly associated with depth of tumor invasion, histological differentiation and TNM stage (all P<0.05) and indicated poor prognosis in patients with GC." (PMID 31897211, 2020). "Another recent study showed that mice deficient for Recql5, the mouse homologue of human RECQL5 are predisposed to a wide variety of other sporadic cancers, establishing this protein as an important tumor suppressor in mice." (PMID 27942286, 2010). "The MRN complex senses DNA DSBs and recruits RECQL5 to sites needing DNA repair This suggests that RECQL5 potentially controls errors in HR, thereby acting as a crucial tumor suppressor." (PMID 35782872, 2022). "Consistent with this it has been suggested that RECQL5 plays a general role in cells as a tumor suppressor and maintainer of genome integrity." (PMID 28100692, 2017). "In the dMMR cases, RECQL5 had the highest percent carrier count and all of the cases with predicted damaging RECQL5 variants had loss of MLH1; however, the same variants were present in several FCCTX and young onset cases with normal tumor expression of MLH1." (PMID 28944238, 2017). "The results of the present study indicate that the RECQL5 gene may be a candidate tumor suppressor gene in the stomach, and that high expression of RECQL5 may limit tumor growth." (PMID 31897211, 2020). "RECQL5 has a tumor-suppressive role in the mouse gastrointestinal tract." (PMID 31897211, 2020). "Conversely, a tumor-promoting function of RECQL5 was reported by several studies." (PMID 31897211, 2020). "In addition, the low expression of RECQL5 protein was associated with poor histological differentiation, deep tumor invasion and high tumor stage, indicating a prognostic role for RECQL5 in preventing GC progression." (PMID 31897211, 2020). "Emerging murine model data suggests RecQ protein-like 5 (RECQL5) is a tumor suppressor gene." (PMID 27942286, 2010). "In the absence of constitutive samples for the NMC cell lines, we cannot definitely determine whether the observed mutation in RECQL5 in each case is somatic or germline, but its detection in 75% of samples suggests that it may play an important role in NMC tumor development and disease progression." (PMID 29348827, 2017). "After adjusting for tumor type, only thoracic cases with high HRD score retained significance with high RECQL5 expression (p = 0.0189)." (PMID 36964191, 2023). "Therefore, the prognostic significance of LIHC was significantly influenced by factors such as pathological stage, tumor status, and the expression levels of RECQL, WRN, RECQL4, and RECQL5." (PMID 37626815, 2023). "Although neither the tumor suppressor function nor the oncogene function of RECQL5 is particularly strong." (PMID 31231988, 2019).
genetic disorders (1 paper, 2021). "Although no genetic disorders have been reported due to loss of RECQL1 or RECQL5, dysfunction of either gene is associated with tumorigenesis." (PMID 33718381, 2021).
RECQL5 also shares sentences with these, for which no sentence is quoted: myocardial infarction (2 papers); blood cancer (1); cardiovascular disease (1); coronary artery disease (1); diabetes mellitus (1); gastric adenocarcinoma (1); head and neck cancer (1); heart disease (1); hereditary diffuse gastric cancer (1); mesothelioma (1); microcephaly (1); osteoporosis (1); prostate carcinoma (1); rhabdomyosarcoma (1); thyroid cancer (1); Werner syndrome (1).